MALAT1 (metastasis associated lung adenocarcinoma transcript 1)
Diseases named in the same sentence as MALAT1 in open-access papers (continued):
Sharing a sentence is not in itself a finding about the gene and the disease.
breast tumor (21 papers, 2016 to 2025). "Whilst MALAT1 has been found to be overexpressed in 14% of breast tumour samples, an alternatively spliced variant of MALAT1 (Δsv-MALAT1) showed decreased expression in a subset of tumours and shows potential as an individual prognostic factor for BC." (PMID 36139550, 2022). "Additional, it has been found that MALAT1 gene mutations frequently occurred in luminal-type breast tumors." (PMID 31795964, 2019). "MALAT1 expression is associated with ERα+/PR+ breast tumors and with lower relapse-free survival (RFS)." (PMID 30545127, 2018). "Our results reveal a complex expression pattern of various MALAT1 transcript variants in breast tumours, and suggest that this pattern of expressions should be taken into account to evaluate MALAT1 as predictive biomarker and therapeutic target." (PMID 27172249, 2016). "MALAT1 (metastasis-associated lung adenocarcinoma transcript 1) is one of the best characterized lncRNAs with roles in neural development and function, retina, myogenesis, and vascular cell proliferation; it is dysregulated in cancers, including upregulation in breast tumors." (PMID 30545127, 2018). "MALAT1 increased breast tumor cell proliferation by miR-124 sponging and activating the CDK4/E2F1 axis." (PMID 36597150, 2023). "According to our data, the frequency of deletions in the locuswhere MALAT1 resides in luminal B breast tumors amounts to18%." (PMID 37538803, 2023). "It usually over-expresses in patients’ tumors and metastases, and the over-expression of lncRNA MALAT1 has been shown to be positively correlated with tumor progression and metastasis in a large number of tumor types, including breast tumors." (PMID 35706002, 2022). "Kim’s study also analyzed the RNA-Seq data from TCGA but reported contradictory findings that MALAT1 was significantly downregulated in human breast tumors compared with normal mammary tissues." (PMID 32708561, 2020). "Kim’s study also reported their data in TCGA, showing that the MALAT1 level was downregulated in human breast tumors compared to normal tissues." (PMID 32708561, 2020). "When the expression of MALAT1 was restored in breast tumor tissue, the distant metastasis in the lung was reduced." (PMID 31214490, 2019). "Patients whose primary breast tumors showed a high expression of NEAT1, colon cancer associated transcript 2 (CCAT2), or metastasis associated lung adenocarcinoma transcript 1 (MALAT1) had shorter overall survival (OS)." (PMID 30545127, 2018). "MALAT1 staining was also higher in formalin-fixed paraffin embedded (FFPE) breast tumors than normal tissue." (PMID 30545127, 2018). "Δsv-MALAT-1 was mainly downregulated in breast tumors, therefore it can serve as an independent prognostic marker." (PMID 27608009, 2016). "To identify the role of MALAT1 in breast tumor progression, we determined the potential changes in the levels of the RNA of interest in a series of BC cell lines of isogenic background." (PMID 27250026, 2016). "Hsa-miR-125b levels were analysed in 20 low-Δsv-MALAT1-expressing (median mRNA value: 0.36) and 20 high-Δsv-MALAT1-expressing breast tumours (median mRNA value: 2.13)." (PMID 27172249, 2016). "In order to determine the prognostic significance of MALAT1 expression pattern in human breast tumours, we analysed MALAT1 mRNA levels in a large series of 446 primary breast tumours from patients with known clinical/pathological status and long-term outcome." (PMID 27172249, 2016). "One study, using deep-sequencing technology, identified MALAT1 as one of the highly expressed lncRNAs in breast tumours." (PMID 27172249, 2016). "This alternative Δsv-MALAT1 transcript was mainly underexpressed (18.8%) in our breast tumour series." (PMID 27172249, 2016). "Among the 446 breast tumour RNA samples tested, 63 (14.1%) tumours showed MALAT1 mRNA overexpression (NMALAT1 from 3.02 to 13.4), and only 13 (2.9%) tumours showed MALAT1 mRNA underexpression (NMALAT1 from 0.15 to 0.32), as compared with normal breast tissues." (PMID 27172249, 2016).
breast tumor (continued). "Silencing of MALAT1 inhibited breast tumor cell proliferation." (PMID 36597150, 2023). "Breast tumors are mostlycharacterized by low Δsv-MALAT1 expression levels." (PMID 37538803, 2023). "The patterns may also change among breast tumor cell lines representing different cancer stages where MALAT1 expression is modulated." (PMID 37367050, 2023). "Taken together, these data show that MDA-MB-231 cells with MALAT1 knockdown had significantly decreased ability to multiply, migrate, and colonize, suggesting that breast tumor malignancy could be mediated by MALAT1." (PMID 34012919, 2021). "All the 446 breast tumour RNA samples tested showed a marked presence of Δsv-MALAT1 transcript." (PMID 27172249, 2016). "MALAT1 was overexpressed in 14% (63/446) of the breast tumours." (PMID 27172249, 2016). "MALAT1 mRNA was detected in all breast tumour samples and also in all normal breast tissues." (PMID 27172249, 2016). "Interestingly, interrogation of dbEST database allowed the identification of an alternatively spliced MALAT1 transcript (Dsv-MALAT1) that was mainly underexpressed in breast tumor samples as compared to full length MALAT1, and which acted as an independent prognostic factor." (PMID 29739426, 2018). "Specifically, a set of lncRNAs were differentially expressed in ER+ and ER– breast tumors, including well-known ones such as NEAT1, MALAT1 and Xist, and also novel lncRNAs LINC01297 and RP11-303E16.2." (PMID 29719633, 2018). "17β-Estradiol treatment affects breast tumor or nontumor cells proliferation, migration, and invasion in an ERα-independent, but a dose-dependent, way by decreasing the MALAT1 RNA level." (PMID 30046354, 2018). "Surprisingly, a significant link was observed between Δsv-MALAT1 underexpression and tumours with large macroscopic size, negative for HRs and expressing high MKI67 mRNA levels, suggesting that underexpression of Δsv-MALAT1 has a role in aggressiveness of breast tumours." (PMID 27172249, 2016).
diabetic cardiomyopathy (20 papers, 2018 to 2025). Diabetic cardiomyopathy is a disorder of the heart muscle in people with diabetes. "Mice studies conveyed a possible role of metastasis-associated lung adenocarcinoma transcript 1 in diabetic cardiomyopathy pathogenesis." (PMID 29998127, 2018). "Similarly, another antisense RNA, MALAT1 (metastasis-associated lung adenocarcinoma transcript 1), is linked to cardiovascular diseases including hypertension and diabetic cardiomyopathy." (PMID 30669611, 2019). "This indicates the possible association of MALAT1 with diabetic cardiomyopathy pathogenesis." (PMID 29998127, 2018). "The knockdown of MALAT1 in the diabetic cardiomyopathy mice model alleviates the clinical manifestations of high glucose on heart muscles, such as inflammation and collagen accumulation, by influencing the Hippo-Yap pathway." (PMID 41256287, 2025). "In cardiomyocytes exposed to high glucose in vitro and in myocardial tissue from mice with diabetic cardiomyopathy in vivo, MALAT1 expression is upregulated." (PMID 41199749, 2025). "Metastasis-associated lung adenocarcinoma transcript 1 (MALAT1), a lncRNA, has emerged as a crucial regulator of apoptosis in diabetic cardiomyopathy through its interaction with enhancer of EZH2." (PMID 37482041, 2023). "Mice studies further illustrated the roles of MALAT1 and myheart where MALAT1 was differentially expressed in diabetic cardiomyopathy mouse models and myheart showed to exhibit cardio protective functions in stressed hearts." (PMID 29998127, 2018). "Another study compared the expression of inflammatory biomarkers like TNF alpha, IL-1beta, and IL-6 in diabetic cardiomyopathy mice in which MALAT1 was knockdown to a control group of diabetic cardiomyopathy mice where MALAT1 expression is intact." (PMID 29998127, 2018). "The MALAT1 level stays upregulated in diabetic cardiomyopathy." (PMID 41256287, 2025). "In our previous studies, several ncRNAs including MIAT, MALAT1, H19 and circHIPK3 have been suggested to participate in the modulation of cardiomyocyte apoptosis and autophagy and consequently result in the development of diabetic cardiomyopathy." (PMID 31240820, 2019). "Malat1 knockdown reduced cell apoptosis of mice cardiomyocytes under high glucose treatment by sponging miR-181a-5p, which may provide a novel target for diabetic cardiomyopathy." (PMID 31694052, 2019). "Additionally, in vivo and in vitro studies of mice model of diabetic cardiomyopathy, Malat1 expression was revealed to be considerably increased." (PMID 31694052, 2019). "Known biomolecules have been hypothesized to affect lncRNA MALAT1; for example, the pineal gland hormone and common sleep aid melatonin were shown to have an antifibrotic effect in a model of diabetic cardiomyopathy by inhibiting lncRNA MALAT1 and miR-141-dependent NLRP3 inflammasome activation." (PMID 38485860, 2024). "LncRNA MALAT1 was significantly upregulated in mice with diabetic cardiomyopathy and in cardiomyocytes induced by high glucose, and knocking down lncRNA MALAT1 expression could significantly improve apoptosis induced by high glucose and inhibit mir-181A-5p expression." (PMID 36225311, 2022).
renal carcinoma (20 papers, 2015 to 2024). A carcinoma arising from the epithelium of the renal parenchyma or the renal pelvis. "Among all the lncRNA candidates predicted by the BiGAN as being associated with renal cancer, 7 lncRNAs were among the top 10 in the predicted list, (MALAT1 1st, HOTAIR 2nd, PVT1 3rd, NBAT1 4th, UCA1 5th, H19 6th, and MEG3 7th)." (PMID 34193046, 2021). "In a recent study, MALAT1 was found to compete with endogenous RNA to regulate ZEB2 expression by sponging with miR-200 s in kidney carcinoma." (PMID 30098599, 2018). "MALAT1 has been shown to promote cancer cell proliferation in a variety of malignancies and acts as an oncogene in renal cancer." (PMID 27458156, 2016). "Then we found that MALAT1 expression correlates with miR- 200s family expression in human renal cancer tissue from TCGA Data Portal." (PMID 26461224, 2015). "Further assay of transwell showed that knockdown MALAT1 suppressed renal cancer cell migration and invasion." (PMID 26461224, 2015). "To explore the role of MALAT1 in renal cancer cells, we stably inhibited MALAT1 in two KIRC cell lines ACHN and 786-O with lenti-viruses carrying shRNA for MALAT1 and a control nonspecific shRNA (LacZ)." (PMID 26461224, 2015). "Our data also confirmed that MALAT1 have higher expression in renal cancer cell lines and renal cancer tissues." (PMID 26461224, 2015). "We then found that knockdown MALAT1 can inhibit renal cancer cell proliferation and metastasis in vitro and in vivo." (PMID 26461224, 2015). "Among these lncRNAs, MALAT1, RCAT1, DUXAP9, TCL6, LINC00342, AGAP2 Antisense1, DLEU2, NNT-AS1, LINC00460, and Lnc-LSG1 are, for example, specific to renal cancer, while changes in HOTAIR, ANRIL, ZFAS1, HOTAIRM1, PVT1, MALAT1, and LNP1 are associated with breast and brain cancer." (PMID 38790894, 2024). "Furthermore, the resistance of renal cancer cells to sunitinib is mediated by the MALAT1/miR-362-3p/G3BP1 signaling axis." (PMID 35706002, 2022). "Interestingly, miR‐182‐5p functioned as a tumor repressor in renal cancer by inhibiting cell proliferation, colony formation through either diminished MALAT‐1 expression or activating AKT/FOXO3a signaling pathway." (PMID 31605468, 2019). "Additionally, our data indicated that knockdown expression of MALAT1 decreased renal cancer cell proliferation, migration and invasion in vivo and in vitro." (PMID 26461224, 2015). "In addition, Malat1 promotes the development of renal carcinoma by interacting with Ezh2." (PMID 35309141, 2022). "Surprisingly, a most recent report shows that MALAT1 promotes the activation of PRC2 by binding to EZH2 and enhances EZH2-mediated repression of Polycomb-dependent target gene E-Cadherin in clear renal cancer." (PMID 26516927, 2015). "In contrast, a recent study reports that MALAT1 can bind to EZH2 and downregulate E-cadherin expression through EZH2-mediated H3K27me3 at the E-cadherin gene promoter in clear renal cancer." (PMID 26516927, 2015). "We transfected miR-200c inhibitor or negative control of the inhibitor to renal cancer cells stably transfected with sh-MALAT1–1 or sh-LacZ." (PMID 26461224, 2015). "To further support this conclusion, we examined the expression of MALAT1 in renal cancer cell lines, renal cancer tissues and their corresponding noncancerous tissues from Tongji Hosptial." (PMID 26461224, 2015). "Whereas in colorectal, lung and renal cancer SFPQ has been reported to act as a transcriptional repressor that serves to dampen proto-oncogene expression, a function that is frequently derailed via the overexpression and binding of oncogenic lncRNAs, such as MALAT-1 and SANT1." (PMID 34218270, 2021).
asthma (18 papers, 2019 to 2024). "This study constructed an asthma-associated competing endogenous RNA network, determined 5 key long non-coding RNAs (MALAT1, MIR17HG, CASC2, MAGI2-AS3, DAPK1-IT1) and identified 8 potential new drugs (Tamoxifen, Ruxolitinib, Tretinoin, Quercetin, Dasatinib, Levocarnitine, Niflumic Acid, Glyburide)." (PMID 31924195, 2020). "In another study, RT-qPCR analysis on blood samples revealed an upregulated MALAT1 in patients with asthma compared to healthy controls." (PMID 37250901, 2023). "In the following sections, we will discuss the involvement of MALAT1 in the pathogenesis of lung diseases, especially asthma, COPD, IPF, ARDS, and PAH." (PMID 37250901, 2023). "When taken together with the three previous studies, it becomes evident that MALAT1 plays a crucial role in the pathogenesis of asthma, as demonstrated through preclinical and clinical investigations." (PMID 37250901, 2023). "For instance, in the asthma study by Yang and Wang detailed above, the knockdown of MALAT1 reversed inflammation and mitigated bronchial and tracheal smooth muscle cell injury through the regulation of miR-133a and RyR2." (PMID 37250901, 2023). "This study proposes a mechanism by which MALAT1 is involved in asthma in newborn rats, which is an intriguing finding." (PMID 37250901, 2023). "First, the authors briefly discussed about how MALAT1 dysregulation can influence the course of asthma and COPD." (PMID 37250901, 2023). "Some studies in multiple sclerosis and asthma showed that lncRNA MALAT1 directly downregulates miR-155 miRNA." (PMID 38006062, 2023). "In bronchial asthma, MALAT1 co-regulates Th2-type hypersensitivity with VEGF, abnormally activates ILC, and causes asthma." (PMID 36419933, 2022). "Inhibiting MALAT1 increases miR-216a to facilitate cell apoptosis and suppress proliferation and migration in asthma AMSCs." (PMID 36186445, 2022). "The expression of MALAT1 is enhanced in patients with asthma and it participates in the regulation of inflammation by sponging miR-155." (PMID 34872453, 2021). "Then by utilizing bioinformatics tools, we constructed a lncRNA-miRNA-mRNA ceRNA network, from which we extracted asthma related DE ceRNA network and recognized 5 potential key lncRNAs (MALAT1, MIR17HG, CASC2, MAGI2-AS3 and DAPK1-IT1)." (PMID 31924195, 2020). "We then constructed a lncRNA-miRNA-mRNA global ceRNA network and extracted asthma-related DE ceRNA network, from which we determined 5 key lncRNAs (MALAT1, MIR17HG, CASC2, MAGI2-AS3, DAPK1-IT1)." (PMID 31924195, 2020). "Among the 5 key lncRNAs, MALAT1 and MIR17HG were thought to be most crucial as they linked to more verified asthma-related miRNAs and mRNAs, also, the functional enrichment results were much abundant than the other 3 lncRNAs." (PMID 31924195, 2020). "Several studies on multiple sclerosis and asthma found that MALAT1 and NEAT1 regulate the RUNX3–GATA3/TBX21 axis, key transcription factors (TFs) in T cell differentiation, by regulating the expression levels of the related miRs, thereby influencing the direction of the Th1/Th2 bias." (PMID 38006062, 2023). "Malat1 has capability to modulate Th1/Th2 balance in asthma via MALAT1/miR-155/CTLA-4 axis." (PMID 35656293, 2022). "LncRNA MALAT1 expression is increased in tracheal tissues of asthma modeling rats." (PMID 36186445, 2022). "The significant role of MALAT1 and miR-155 in asthma has been universally demonstrated." (PMID 34970542, 2021). "The mechanisms of action of MALAT1 in tumor progression and metastasis remain unclear and even less is known about its effects in inflammatory disease states like asthma." (PMID 32292999, 2020). "There is increasing evidence that the lncRNA–miRNA–mRNA axis is involved in asthma pathogenesis, for example, MEG3 and MALAT1 are involved." (PMID 36463267, 2022). "MALAT1 inhibitors are currently available for the treatment of certain cancers, but have not been used for the treatment of asthma." (PMID 36419933, 2022).
asthma (continued). "MALAT1 and MIR17HG had many common enrichment results that were important in asthma." (PMID 31924195, 2020). "Therefore, MALAT1 can positively or negatively regulate ALI and chronic lung diseases (e.g., chronic obstructive pulmonary disease (COPD), bronchopulmonary dysplasia (BPD), pulmonary fibrosis, asthma, and pulmonary hypertension (PH))." (PMID 36186445, 2022). "However, whether targeting the MALAT1/miR-155/CTLA-4 axis can change Th2-dependent response that promotes airway inflammation in asthma is not completely clear and needs further study." (PMID 34635022, 2021). "However, in fact, the exact role of Malat1 in asthma has not been reported." (PMID 31695627, 2019). "The relationship between MALAT1 and CTLA4 is not previously studied in cancer; however, its data in asthma showed that MALAT1 sponges miR-155 upregulating CTLA4." (PMID 36387279, 2022). "No study had assessed lncRNA MALAT1, MIR17HG, CASC2, MAGI2-AS3 and DAPK1-IT1 in asthma." (PMID 31924195, 2020). "However, there is no report about the regulation of Malat1 on ASMC proliferation and migration in asthma." (PMID 31695627, 2019).